GGTA1 (glycoprotein alpha-galactosyltransferase 1 (inactive))
Synonyms: GGTA1P; GGTA; GLYT2; a1/3GTP
Tractability: Antibody: UniProt predicts a signal peptide or a membrane-spanning region; the Human Protein Atlas places it where antibodies can reach.
Gene: Protein-coding gene on chromosome 9 (121,444,991 to 121,500,032, reverse strand). Ensembl gene ENSG00000204136.
Subcellular location: Golgi apparatus, Golgi stack membrane
Subcellular location (Human Protein Atlas): Cytosol; Plasma membrane
Gene Ontology:
Biological process: leukotriene D4 biosynthetic process
Cellular component: Golgi cisterna; Golgi cisterna membrane
Diseases named in the same sentence as GGTA1 in open-access papers:
GGTA1 is named in the same sentence as 14 diseases in open-access papers, as found by Europe PMC text mining. Sharing a sentence is not in itself a finding about the gene and the disease. The quoted sentences say what the papers report.
Cerebral ischemia (2 papers, 2021 to 2025). Restriction of arterial blood supply to the brain associated with insufficient oxygenation to support the metabolic requirements of the tissue. "Ggta1 responds to cerebral ischemia and its downregulation has been linked to protective preconditioning effects." (PMID 40791429, 2025).
Allergy (1 paper, 2024). An allergy is an immune response or reaction to substances that are usually not harmful. "Here, we describe a new animal model of red meat allergy using percutaneous α-Gal sensitization of gene-edited GGTA1-deficient pigs." (PMID 38469303, 2024).
Autoimmunity (1 paper, 2021). The occurrence of an immune reaction against the organism's own cells or tissues. "anti-Gal antibody is shown to maintain the immunological balance between autoimmunity and infection in humans, and Ggta1 knockout in mice promotes anti-Gal-mediated increase in immunogenicity." (PMID 34591125, 2021).
bacterial sepsis (1 paper, 2021). "We propose that Ggta1 deletion in mice increases resistance to bacterial sepsis via two distinct antibody-dependent mechanisms." (PMID 34009123, 2021). "Given the fitness cost imposed by bacterial sepsis, we infer that the observed reduction in microbiota pathogenicity upon Ggta1 deletion in mice may have contributed to increase the frequency of GGTA1 loss-of-function mutations in ancestral primates that gave rise to humans." (PMID 34009123, 2021).
medulloblastoma (1 paper, 2025). A malignant, invasive embryonal neoplasm arising from the cerebellum. "This differential expression suggests that GGTA1 may not play an active role in promoting medulloblastoma, and its lower expression in tumor tissues could indicate a reduced involvement in tumor progression." (PMID 40104502, 2025).
Sepsis (1 paper, 2021). Sepsis is defined as life-threatening organ dysfunction caused by a dysregulated host response to infection. "We infer that ancestral Old World primates carrying loss-of-function mutations in GGTA1 probably shaped their microbiota to minimize its pathogenic effect, providing a major fitness advantage against sepsis." (PMID 34009123, 2021). "We propose that GGTA1 loss-of-function mutations conferred a selective benefit during primate evolution, in part, by shaping commensal bacteria in the microbiota to mitigate the pathogenesis of sepsis." (PMID 34009123, 2021). "We then asked whether the Ig-dependent shaping of the microbiota in Ggta1-/- mice affects the pathogenesis of sepsis due to systemic infections emanating from gut microbes." (PMID 34009123, 2021).
Thrombocytopenia (1 paper, 2022). A reduction in the number of circulating thrombocytes. "Although the survival time of the pig cardiac xenograft with six-gene modifications (GGTA1-/-/hCD46/hCD55/hTBM/hCD39/hEPCR or GGTA1-/-/hCD46/hCD55/hEPCR/hCD47/hTFPI) in the baboon was only 200 days, no significant coagulopathy or consumptive thrombocytopenia was observed in the six-transgene cohort." (PMID 36561750, 2022).
infection (3 papers, 2021 to 2023). The state of being infected such as from the introduction of a foreign agent such as serum, vaccine, antigenic substance or organism. "Here we provide experimental evidence for yet another fitness advantage against infection, associated with the loss of GGTA1, driven by Ig-shaping and reduction of microbiota pathogenicity." (PMID 34009123, 2021). "(D) Schematic showing infection of Rag2-/-Ggta1+/+ mice with a cecal inoculum from either Ggta1+/+ or Rag2-/-Ggta1+/+ mice." (PMID 34009123, 2021). "(E) Survival of Rag2-/-Ggta1+/+ (n = 5) mice after infection with a cecal inoculum from Ggta1+/+ mice, and Rag2-/- Ggta1+/+ (n = 5) mice after infection with a cecal inoculum from Rag2-/-Ggta1+/+ mice; one experiment." (PMID 34009123, 2021). "(B) Survival of Rag2-/-Ggta1-/- (n = 9) mice after infection with a cecal inoculum from Ggta1-/- mice, and from Rag2-/-Ggta1-/- (n = 9) mice after infection with a cecal inoculum from Rag2-/-Ggta1-/- mice; two experiments." (PMID 34009123, 2021). "(F) CFU of Ae and An bacteria in Rag2-/-Ggta1-/- mice (n = 4 per group), 24 hr after infection as in (E); one experiment." (PMID 34009123, 2021). "Of note, this pathobiont can induce a systemic αGal-specific NAb response in humans as well as in Ggta1-deleted mice, which is protective against infection by pathogens expressing αGal-like glycans." (PMID 34009123, 2021). "(A) Schematic showing infection of Rag2-/-Ggta1-/- mice with a cecal inoculum from either Ggta1-/- or Rag2-/-Ggta1-/- mice." (PMID 34009123, 2021). "(C) Colony-forming units (CFU) of aerobic (Ae) and anaerobic (An) bacteria in Rag2-/-Ggta1-/- mice (n = 5 per group), 24 hr after infection as in (B); two experiments." (PMID 34009123, 2021). "While loss-of-function mutations in genes encoding glycosyltransferases can provide fitness advantages against infection, these can compromise the physiologic functions of the eliminated self-glycan, as illustrated by the occurrence of reproductive senescence upon Ggta1 deletion in mice." (PMID 34009123, 2021). "(H) CFU of Ae and An bacteria in Ggta1-/- mice receiving vehicle (PBS) (n = 4–5) or Anti-Gr1 Ab (n = 4–5), 24 hr after infection as in (G); five experiments." (PMID 34009123, 2021). "(G) Survival of Ggta1-/- mice receiving vehicle (PBS) (n = 9) or Anti-Gr1 Ab (n = 8), 24 hr before infection with cecal inoculum from Ggta1-/- mice; two experiments." (PMID 34009123, 2021). "To test this hypothesis, we compared the outcome of Rag2-/-Ggta1-/- mice upon a systemic infection by Ig-shaped vs. a non-Ig-shaped microbiota." (PMID 34009123, 2021).
neurodegenerative disease (2 papers, 2022 to 2023). A disorder of the central nervous system characterized by gradual and progressive loss of neural tissue and neurologic function. "Decreased expression of pro-inflammatory genes, which are associated with neurodegenerative disease or astrocyte and microglia phenotypes Cd40, C1qB, Cd68, Cd45, Aqp-4, Il1α, Fkbp5, Ggta1, Cd16, H2-T23, and Serping1, was observed following C-32:6 treatment and C1qC, Tspo, and Gbp2 with FFA C-34:6." (PMID 37740008, 2023).
tumor (2 papers, 2025). "The expression of GGTA1 is negatively correlated with TMErisk scores, suggesting its potential protective role against tumor development." (PMID 40104502, 2025). "GGTA1: Medium expression of GGTA1 is observed in normal tissues (HPA023262), while low expression is detected in tumor tissues." (PMID 40104502, 2025). "In the GGTA1-knockout mouse model, animals were treated with PBS, Ad35(Luc), Adf35(O), Adf35(OG), Adf35(ON) and Adf35(OGN) respectively (n = 2 in each group), after immunization to generate anti-α-gal antibodies and tumor implantation." (PMID 39934471, 2025).
GGTA1 also shares sentences with these, for which no sentence is quoted: coronary artery disease (1 paper); influenza (1); ischemic stroke (1); Stroke (1).